OPRK1 (opioid receptor kappa 1)
Diseases named in the same sentence as OPRK1 in open-access papers (continued):
Sharing a sentence is not in itself a finding about the gene and the disease.
hepatocellular carcinoma (4 papers, 2017 to 2021). A malignant tumor that arises from hepatocytes. "Interestingly, the low level of OPRK1 was associated with a poor prognosis in hepatocellular carcinoma, while in lung cancer and melanoma it led to the growth of cancer cells." (PMID 34768458, 2021).
prostate carcinoma (4 papers, 2011 to 2025). A carcinoma that arises from epithelial cells of the prostate gland. "Opioid receptors have been heavily linked to prostate cancer biology and some have been proposed as potential targets such as OPRK1 which hints at the possibility of NPBWR1 being able to be targeted in a similar way." (PMID 38983753, 2024). "Loss of OPRK1 function delays castration-resistance and inhibits castration-resistant growth of prostate cancer cells in culture and in vivo, suggesting OPRK1 as a therapeutic target." (PMID 35365763, 2022). "Immunohistochemical analysis showed that expression of OPRK1, a G protein-coupled receptor, was upregulated in human prostate cancer tissues after preoperative androgen derivation or CRPC progression." (PMID 35365763, 2022). "Furthermore, several genes including FZD4, OPRK1 and OXTR identified here with a growth inhibitory loss-of-function impact on the prostate cancer cells have been recently associated in independent studies with a role in prostate cancer pathogenesis." (PMID 21443765, 2011). "Taken together, OPRK1 is induced by androgen deprivation therapy (ADT) and can be a promising therapeutic target of human prostate cancer treated with ADT." (PMID 35365763, 2022).
substance abuse (4 papers, 2018 to 2024). The use of a drug for a reason other than which it was intended or in a manner or in quantities other than directed. "Some of us previously investigated involvement of eight genes in the opioid system (OPRD1, OPRK1, OPRL1, OPRM1, PDYN, PENK, PNOC, and POMC) and their potential effects on substance abuse." (PMID 34440333, 2021).
lung carcinoma (3 papers, 2017 to 2021). "In previous studies, κ-opioid receptors 1 (OPRK1) were shown to suppress lung cancer growth, suggesting a tumor-suppressive gene." (PMID 34804019, 2021).
opioid use disorder (3 papers, 2024 to 2025). A substance-related disorder that involves the recurring use of opioids despite negative consequences. "While some findings indicate KORs could influence initial susceptibility to opioid use disorder (OUD), few studies have examined whether variations in the gene encoding the receptor (OPRK1) relate to clinically-relevant behavioral variation among current opioid users." (PMID 41394155, 2025).
Alzheimer disease (2 papers, 2022). A progressive, neurodegenerative disease characterized by loss of function and death of nerve cells in several areas of the brain leading to loss of cognitive function such as memory and language. "The OPRK1 gene encodes an opioid receptor, and methylation of the gene has been linked to the development of Alzheimer's disease." (PMID 36341127, 2022).
colorectal cancer (2 papers, 2017 to 2024). A primary or metastatic malignant neoplasm that affects the colon or rectum. "Since Oprk1, an opioid receptor subunit, which is overexpressed in liver metastasis of colorectal cancer was also increased in LLRCs, one could speculate that a subset of signaling pathways active in neurons also define the specific properties of LLRCs50." (PMID 28084309, 2017).
pancreas neuroendocrine tumours (2 papers, 2022 to 2023). "It has been reported that it was highly expressed in small bowel neuroendocrine tumors and pancreatic neuroendocrine tumors and can predict primary tumors according to the expression of OPRK1 in metastatic tumors, which is expected to become a new promising therapeutic target." (PMID 35535346, 2022).
preeclampsia (2 papers, 2022 to 2023). Preeclampsia is a hypertensive disorder of pregnancy that is characterized by new-onset hypertension with proteinuria presenting after 20 weeks of gestation, and depending on mild or severe forms may initially present with severe headache, visual disturbances, and hyperreflexia. "In summary, we identified three key inflammation-associated genes, namely INHBA, OPRK1, and TPBG, which can be used as potential genetic biomarkers for preeclampsia prediction and treatment, and established a nomogram as a predictive model." (PMID 35880174, 2022). "The authors found that the INHBA gene together with the OPRK1 and TPBG genes are key inflammation-related genes that affect the course of pregnancy (the expression of INHBA and TPBG genes in complicated preeclampsia pregnancy is higher, and the OPRK1 gene is lower, compared with normal pregnancy)." (PMID 37511900, 2023). "OPRK1 has been correlated with oxidative stress in experimental research, which may be relevant to the development of preeclampsia." (PMID 35880174, 2022). "However, the specific mechanism of OPRK1 in preeclampsia needs to be further investigated." (PMID 35880174, 2022). "The expression of INHBA, OPRK1, and TPBG showed significant differences between preeclampsia and non-preeclampsia samples." (PMID 35880174, 2022). "The binding energy between curcumin and TPBG-4cnc, OPRK1-4djh, and RELA-3qxy was less than −7.0 kcal/mol, which further suggested the effectiveness of curcumin for the treatment of preeclampsia." (PMID 35880174, 2022). "We further analyzed INHBA, OPRK1, and TPBG, which played a crucial role in the development of preeclampsia." (PMID 35880174, 2022). "Subsequently, we analyzed the expression of INHBA, OPRK1, and TPBG in preeclampsia placental tissue and non-preeclampsia placental tissue." (PMID 35880174, 2022). "The binding affinity for curcumin and TPBG-4cnc, OPRK1-4djh, and RELA-3qxy was less than −7.0 kcal/mol, indicating that they have strong binding energy, which further suggests the effectiveness of curcumin in the treatment of preeclampsia." (PMID 35880174, 2022). "There is no information on studies directly related to OPRK1 and preeclampsia." (PMID 35880174, 2022).
type 2 diabetes (2 papers, 2018 to 2024). "Examples of predicted applicable diseases of sinomenine are adiposity and type II diabetes mellitus, implying that sinomenine is effective for treatment of adiposity and type II diabetes mellitus based on the target proteins: GAA, OPRM1, OPRD1, OPRK1." (PMID 30046160, 2018).
behavioral addiction (1 paper, 2019). "A backward stepwise regression analysis identified age, male sex, dopamine replacement therapy and ADRA2C, DRD2, DDC, HTR2A and OPRK1 genotypes as significant predictors of behavioral addiction / impulse control disorders." (PMID 33324875, 2019).
bone metastasis (1 paper, 2017). Transfer of a neoplasm from its primary site to bones. "An association between the rs1051660 in the OPRK1 and bone metastasis in cancer patients was found in this investigation." (PMID 29259946, 2017).
Dyskinesia (1 paper, 2023). A movement disorder which consists of effects including diminished voluntary movements and the presence of involuntary movements. "A variety of ADRs belonging to movement disorders (e.g., extrapyramidal disorder, Parkinsonism, and dyskinesia) were associated with several targets, including OPRK1 (9 drugs), CHRM2 (8 drugs), and ADRA1A (5 drugs)." (PMID 37468498, 2023).
endometrial cancer (1 paper, 2021). Primary or metastatic malignant neoplasm involving the endometrium (mucous membrane that lines the endometrial cavity). "Our results indicate that OPRK1 is overexpressed in endometrial cancer, which may be due to decreased miR-124-3p.1 levels." (PMID 34768458, 2021). "In addition, decreased levels of miR-124-3p.1 may result in increased OPRK1 expression, contributing to endometrial cancer progression." (PMID 34768458, 2021). "Expression of CXCL12, OPRK1, DRD5, COMT, DRD2, and DRD3 proteins was assessed in the serum of endometrial cancer patients and control group using ELISA." (PMID 34768458, 2021). "It has been observed that as endometrial cancer progresses, expression of CXCL12, GNAL, OPRK1, DRD2, and DRD3 increases while DRD5 and COMT levels are gradually reduced." (PMID 34768458, 2021).
fibrosis (1 paper, 2014). the formation of excess fibrous connective tissue in an organ or tissue in a reparative or reactive process. "Comparison of gastric samples collected from patients with fibrosis and samples from those without fibrosis showed the mRNAs for NTS and OPRK1 genes were more than 5-fold upregulated in presence of fibrosis (p < 0.02)." (PMID 24716593, 2014).
hyperhomocysteinemia (1 paper, 2021). A serious metabolic condition caused by mutations in the MTHFR gene, medications, or nutritional deficiency. "Likewise, there is some consistent evidence in the heritability of impulse control disorder via Opioid Receptor Kappa 1 (OPRK1), 5-Hydroxytryptamine Receptor 2A (HTR2a) and Dopa decarboxylase (DDC) genotypes, and hyperhomocysteinemia via the Methylenetetrahydrofolate reductase (MTHFR) gene." (PMID 34281267, 2021).
ovarian carcinoma (1 paper, 2023). A malignant neoplasm originating from the surface ovarian epithelium. "Gene expression levels for OPRK1 and GABRB1 were extremely low in healthy cells and upregulated in ovarian cancer cisplatin-sensitive and -resistant cells." (PMID 37873862, 2023).
peripheral nerve injury (1 paper, 2017). Injury to a peripheral nerve. "Dnmt3a, an epigenetic repressor, participates in epigenetic silencing of several genes (such as Oprk1 and Kcna2 besides Oprm1) in the injured DRG following peripheral nerve injury." (PMID 29170626, 2017).
prostate adenocarcinoma (1 paper, 2025). "Our study identifies OPRK1, a G protein-coupled receptor, as a critical mediator of lineage switching from AR+ prostate adenocarcinoma to NEPC." (PMID 41353213, 2025). "By binding SLC9A3R1 to activate autophagy and destabilize REST, OPRK1 reprograms prostate adenocarcinoma cells toward a NE lineage, thereby fueling ARPI resistance." (PMID 41353213, 2025).
small cell lung carcinoma (1 paper, 2025). Small cell lung cancer (SCLC) is a highly aggressive malignant neoplasm, accounting for 10-15% of lung cancer cases, characterized byrapid growth, and early metastasis. "GSEA further revealed enrichment of neuronal differentiation–related signatures (e.g., neuron fate commitment, neuropilin binding) and the small cell lung cancer gene set in OPRK1-overexpressing cells." (PMID 41353213, 2025).
cancer (20 papers, 2012 to 2025). A tumor composed of atypical neoplastic, often pleomorphic cells that invade other tissues. "The results also revealed a decrease in KCNA2, SNCG, and TGFB2 levels with a simultaneous increase in GNB1, CXCL12, SNCA, and OPRK1 expression in G2 cancer compared to control." (PMID 34768458, 2021). "The objective of this study was to determine the possible association of variations in the OPRM1, OPRK1 and COMT genes with morphine dosing for opioid therapy in Tunisians cancer patients." (PMID 29259946, 2017). "This study might propose the relationship between the roles of OPRK1 on tumor progression and the impact of anesthesia or analgesia management on cancer prognosis." (PMID 34461834, 2021). "OPRK1 knockdown could inhibited cell viability and migration in cancer cells, accompanied with the decreased proteins and genes expression of N-cadherin, Snail, MMP2 and Vimentin, while the E-cadherin expression was increased." (PMID 34461834, 2021). "Interestingly, the cell viability was stable in MCF-10A cells after OPRK1 down-regulation, whereas it was inhibited in cancer cells." (PMID 34461834, 2021). "And OPRK1 expression shows the correlation with tumor progression in various cancers." (PMID 34461834, 2021). "This study also might propose the relationship between the roles of OPRK1 on tumor progression and the impact of anesthesia or analgesia management on cancer prognosis." (PMID 34461834, 2021). "In addition to higher DOR expression, data mining revealed that various aggressive cancer types also overexpress κ- (KOR, OPRK1) and μ- (MOR, OPRM1) opioid receptors." (PMID 33465556, 2021).
tumor (15 papers, 2012 to 2025). "In vivo xenograft models, OPRK1 loss significantly impaired tumor growth, as reflected by reduced tumor volume and weight." (PMID 41353213, 2025). "And our results showed that OPRK1 expression was higher than normal human mammary epithelial cells and was associated with tumor proliferation and migration." (PMID 34461834, 2021). "Critically, the analyses herein have identified OPRK1 as a potential novel therapeutic target; notably, OPRK1 expression was upregulated upon castration, and its loss of function retarded acquisition of CR progression by blocking cell proliferation and tumor growth in multiple CRPC models." (PMID 35365763, 2022). "Consistent with in vitro findings, OPRK1-overexpressing xenografts displayed robust castration-independent growth, in stark contrast to the minimal tumor development observed in the control group." (PMID 41353213, 2025). "Further Western blotting and IHC of tumor tissues further confirmed suppression of OPRK1, SLC9A3R1, NE, autophagy, and EMT markers, together with restoration of REST protein levels." (PMID 41353213, 2025). "In summary, these findings identify OPRK1 as a critical regulator of NE differentiation, stemness, and tumor aggressiveness in PCa." (PMID 41353213, 2025). "In the case of OPRK1, only 50% of tumours expressed this antigen in more than 75% of cells, but its expression profile against healthy tissue was excellent compared to other targets, including FRα." (PMID 37873862, 2023). "The selective inhibition on cell viability of OPRK1 knockdown suggested the correlation between OPRK1 expression and tumor proliferation." (PMID 34461834, 2021). "OPRK1 inhibition can also be expected to suppress tumor growth after CRPC progression." (PMID 35365763, 2022). "After knockdown of OPRK1, the cell viability and tumor migration were decreased notably." (PMID 34461834, 2021). "Therefore, the OPRK1 suppression combined with AKT inhibition might be a strategy to against tumor growth, proliferation and migration." (PMID 34461834, 2021). "However, in normal human mammary epithelial cells MCF-10A, the cell viability was not influenced by OPRK1 siRNA, indicating that the effect of OPRK1 on cell viability might be different between normal cells and tumor cells." (PMID 34461834, 2021). "Compared with controls, enforced OPRK1 expression markedly enhanced cell proliferation (CCK8 and EdU), colony-forming ability, and tumor-sphere formation." (PMID 41353213, 2025).
neurological disorders (3 papers, 2020 to 2025). "We evaluated JTC-801, a small-molecule OPRK1 antagonist originally developed for neurological disorders." (PMID 41353213, 2025).
adenocarcinoma (1 paper, 2025). A common cancer characterized by the presence of malignant glandular cells. "Analysis of the Beltran 2016 cohort demonstrated significantly higher OPRK1 mRNA in NEPC compared with CRPC-adenocarcinoma (CRPC-AD)." (PMID 41353213, 2025). "Independent validation using GSE66187 confirmed elevated OPRK1 expression in NEPC relative to adenocarcinoma." (PMID 41353213, 2025).
OPRK1 also shares sentences with these, for which no sentence is quoted: Pruritus (21 papers); respiratory depression (18); mood disorder (15); alcohol use disorder (9); alcoholism (9); psychiatric disorder (9); schizophrenia (7); atopic dermatitis (5); cocaine dependence (5); epilepsy (5); multiple sclerosis (5); opioid dependence (5); psoriasis (5); irritable bowel syndrome (4); ischemia (4); osteoarthritis (4); anxiety disorder (3); bipolar disorder (3); chronic kidney disease (3); demyelinating disease (3); dysphoria (3); insomnia (3); alcohol addiction (2); bone cancer (2); Borderline personality disorder (2); cholestasis (2); cocaine abuse (2); cognitive decline (2); demyelination (2); dermatitis (2).
A further 75 diseases each share a sentence with OPRK1 in 2 papers or fewer.